CXCL1 (C-X-C motif chemokine ligand 1)
Diseases named in the same sentence as CXCL1 in open-access papers (continued):
Sharing a sentence is not in itself a finding about the gene and the disease.
hepatocellular carcinoma (39 papers, 2012 to 2026). A malignant tumor that arises from hepatocytes. "As such, high tumoral CXCL1 expression was associated with increased tumor aggressiveness and poor outcomes in hepatocellular carcinoma (HCC)." (PMID 36077611, 2022). "Overexpression of CXCL1 is associated with tumor progression and poor prognosis in hepatocellular carcinoma." (PMID 32337262, 2020). "In the present study, we investigated the influence of the CXCL1 rs4074 polymorphism on the occurrence of alcohol induced liver cirrhosis and hepatocellular carcinoma (HCC)." (PMID 24260493, 2013). "It has been reported that expression of CXCL1 is associated with hepatocellular carcinoma survival." (PMID 27419373, 2016). "CXCL1 has also been identified as a serum biomarker associated with hepatocellular carcinoma (HCC)." (PMID 24260493, 2013). "For example, patients with hepatocellular carcinoma who had low blood CXCL1 levels after stereotactic body radiotherapy were more likely to have liver toxicity 3 months following the therapy." (PMID 40427171, 2025). "We then directly used the Transwell assay, a well-established model for examining cell migration following CXCL1 treatment in hepatocellular carcinoma cells." (PMID 39132161, 2024). "Previous studies have revealed that EGF increases the production of CXCL1 in hepatocellular carcinoma cells." (PMID 38713320, 2024). "These outcomes emphasize the critical function of ICAM-1 in the metastatic progression of hepatocellular carcinoma facilitated by CXCL1." (PMID 39132161, 2024). "It was shown that the accumulation of acetyl-Co-A induces an increase in the expression of the CXCL1 gene, which recruits TANs and leads to the formation of extracellular neutrophil traps, which promote the metastasis of hepatocellular carcinoma." (PMID 39408564, 2024). "Knockdown of CXCL1 in Huh7 and Hep3B cells, which express CXCL1 at the highest levels, resulted in reduced migration of hepatocellular carcinoma cells." (PMID 39132161, 2024). "The targeted silencing of CXCL1 detected in our search was shown to inhibit the tumor growth in hepatocellular carcinoma." (PMID 35585513, 2022). "The RIP3 deletion in hepatocellular carcinoma (HCC) is revealed to increase the production of chemokine the CXCL1 by activating the NF-κB pathway, which results in chemoattracting CXCR2+MDSC into cancer site." (PMID 34689842, 2021). "Kaplan-Meier analysis revealed worse overall survival rates in the high CXCL1 expression group, suggesting its potential as a biomarker for cancer progression and stimulating hepatocellular carcinoma cells with CXCL1 enhanced migration abilities by upregulating ICAM-1 expression." (PMID 39132161, 2024). "This suggests that CXCL1 promotes the migration of hepatocellular carcinoma cells." (PMID 39132161, 2024). "However, there is limited research on the role of CXCL1 in the metastasis of hepatocellular carcinoma." (PMID 39132161, 2024). "Therefore, this study mainly explores the role of CXCL1 in promoting hepatocellular carcinoma metastasis." (PMID 39132161, 2024). "This study provides novel evidence that CXCL1 could serve as a therapeutic target for metastasis in hepatocellular carcinoma." (PMID 39132161, 2024). "It has also been suggested that CXCL1 promotes tumor growth in hepatocellular carcinoma (HCC)." (PMID 36614235, 2023). "In addition, SLC7A2 can down-regulate the expression of CXCL1 to inhibit the infiltration of myeloid-derived suppressor cells and the immune escape of hepatocellular cancer." (PMID 36639771, 2023). "Similarly, in gastric, colorectal, and hepatocellular carcinoma serum CXCL1 and CXCL2 correlate with tumor size, metastasis, and decreased overall survival." (PMID 35332119, 2022). "CXCL1 up-regulation may contribute to both the development and progression of hepatocellular carcinoma." (PMID 29283424, 2017).
hepatocellular carcinoma (continued). "It has been reported that CXCL1/CXCR2 density is strongly associated with the number of neutrophils in the tumor microenvironment and can be an independent factor for predicting the prognosis of patients with hepatocellular carcinomas." (PMID 27446967, 2016). "Coincidentally, high expression levels of CXCR2 ligands, such as CXCL1, and CXCL2, have been found to be associated with the growth, invasion, and metastasis of hepatocellular carcinoma (HCC)." (PMID 36797756, 2023). "In this study, we investigated the value of measurement of the chemokine CXCL1 in clinical management of hepatocellular carcinoma (HCC) and its possible role in the molecular pathogenesis of HCC." (PMID 27542259, 2016). "A study in hepatocellular carcinoma reported that gefitinib significantly inhibits the upregulation of VEGF and CXCL1 induced by EGF stimulation, thereby suppressing angiogenesis." (PMID 38918360, 2024). "This study focused on the role of microRNAs in CXCL1-mediated ICAM-1 expression and cell motility in human hepatocellular carcinoma." (PMID 39132161, 2024). "In conclusion, our findings have revealed that CXCL1 downregulates the expression of miR-30b-5p, leading to increased expression of ICAM-1, thereby promoting the motility of hepatocellular carcinoma cells." (PMID 39132161, 2024). "Our research revealed that CXCL1 increases ICAM-1 levels, and the utilization of ICAM-1 siRNA diminished ICAM-1 expression and reduced the CXCL1-stimulated migration in hepatocellular carcinoma cells." (PMID 39132161, 2024). "In hepatoma cell cultures, SASP factors, including CSF1, MCP1, CXCL1 and IL‐15, as well as adhesion molecules such as Icam1 and Vcam1, have been observed to attract a spectrum of immune cell types, encompassing macrophages, NK cells and neutrophils." (PMID 39270064, 2024). "Recently, an increasing number of studies have demonstrated that CXCL1 is involved in pathogenesis in liver disease, including in alcoholic liver injury, nonalcoholic steatohepatitis (NASH), and hepatocellular carcinoma (HCC)." (PMID 34395462, 2021). "Additionally, in HrasG12V‐mutated hepatocellular carcinoma (HCC), senescent HCC cells secrete SASP factors (such as CCL2, IL‐15 and CXCL1) that activate macrophages, neutrophils and NK cells, thereby mediating innate immunity and suppressing tumour progression." (PMID 39270064, 2024). "Furthermore, the miR-30b-5p mimic significantly suppressed CXCL1-promoted ICAM-1 production and cell migration in hepatocellular carcinoma cells." (PMID 39132161, 2024). "In addition, it has been reported thatg9a-mediated H3K9me2 silences the expression of SLC7A2 in hepatocellular carcinoma (HCC), which results in the upregulation of CXCL1 expression and recruitment of MDSCs." (PMID 39080807, 2024). "For instance, M2 TAMs release paracrine factors, CXCL1 and CXCL2, which enhance resistance to sorafenib (SOR) in advanced-stage hepatocellular carcinoma (HCC) cells." (PMID 39919692, 2025). "However, the role of CXCL1 in ICAM-1 expression and in metastasis of hepatocellular carcinoma remains unclear." (PMID 39132161, 2024). "In addition, overexpression of CXCL1 in HepG2 and HepG2/C3A cells (which have the lowest CXCL1 expression) or the knockdown of CXCL1 in Huh7 and Hep3B cells (which have the highest CXCL1 expression), respectively, promoted and reduced ICAM-1 protein expression in hepatocellular carcinoma cells." (PMID 39132161, 2024). "Moreover, in hepatocellular carcinoma (HCC), G9a silences SLC7A2 expression to induce CXCL1, promoting the recruitment of bone marrow-derived suppressor cells (MDSC) to the microenvironment." (PMID 36713412, 2022). "The release of murine CXCL1 (KC, keratinocyte-derived chemokine) was found attenuated by ADAM8 knockdown in murine hepatoma and endothelial cells but not in stellate cells." (PMID 33814981, 2021).
Arthritis (37 papers, 2005 to 2025). Inflammation of a joint. "Protection against serum‐induced arthritis in Ahr‐deficient mice likely reflects a reduced expression of major pro‐inflammatory cytokines and chemokines (such as CXCL1) masking the loss of IL‐22 anti‐inflammatory properties in the animals." (PMID 33734594, 2021). "IL-17A, a major cytokine involved in arthritis, upregulates CXCL1, which is known to cause increased cell migration, angiogenesis, and activation of the STAT-3 pathway." (PMID 27102666, 2016). "The induction and maintenance of joint pain are associated with intense CXCL1-mediated neutrophil influx and production of hyperalgesic mediators, such as IL-1β, and blockade these mediators have been described to suppressed joint pain and damage in murine model of arthritis." (PMID 33995086, 2021). "However, most early arthritis genes in clusters C and D showed an expression peak later, at the acute phase of inflammation, and encoded chemokine receptors (Ccr2 and Ccr5) and chemokine ligands (Cxcl1, Ccl2, Ccl7, and Ccl9)." (PMID 15743466, 2005). "In models of collagen-induced arthritis, C. aerofaciens exacerbates the condition by increasing gut permeability and enhancing the expression of IL-17, CXCL1, and CXCL5 in intestinal epithelial cells." (PMID 40261026, 2025). "Since CXCL5 produces a significantly higher Ca2+ response than CXCL1 and makes significant contributes to gout arthritis pain, we therefore especially focused on CXCL5 in our following studies." (PMID 38627393, 2024). "To further assess the severity of arthritis, we measured the mRNA levels of a variety of pro-inflammatory cytokines and chemokines, including Il18bp, Il18, Il1b, Il6, Il1r2, Ifng, Cxcl9, Cxcl1, and Cxcl2 in arthritic joints of IL-18BP KO and WT littermates." (PMID 37415987, 2023). "CXCL1 has been shown to have neutrophil chemoattractant activity in inflamed tissue in arthritis following activation of the CXCR2 receptor." (PMID 37936684, 2023). "The role of neutrophils or monocytes in arthritis also needs to be tested, as the chemoattractant CXCL1 and CXCL2 were up-regulated in DNase II−/−STINGS365A/S365A mouse paws." (PMID 34901991, 2022). "Arthritis induction led to high levels of IL-1β, CXCL1 (chemokine (C–X–C motif) ligand 1), IL-6, TNF-α, and VEGF, which were markedly decreased after BPI treatment three-, two-, two-, 15-, and threefold, respectively." (PMID 36361854, 2022). "In LPS-induced inflammation models, as well as an arthritis model and in macrophages, CXCL1 production is strongly decreased by IL-37." (PMID 34029331, 2021). "The release of IL-6 and CXCL1/KC to the synovial fluid increased 7 days after induction of arthritis, albeit CXCL1/KC concentration was just slightly above the detection limit." (PMID 28587618, 2017). "We also determined that 17R-RvD1 reduced systemic KC (CXCL1) levels, a principal chemokine that recruits neutrophils, and downregulated Il1b transcripts, a key cytokine that amplifies arthritis." (PMID 27158677, 2016). "It has been reported that CXCL1 can mediate neutrophil migration in models of mouse lung inflammation and experimental arthritis." (PMID 26503598, 2015). "Using in vitro cultured primary human osteoblasts and an in vivo rat CIA model, another study demonstrated that EGCG was able to ameliorate arthritis in rats, associated with reduced MCP-1/CCL2 and GRO/CXCL1 synthesized by osteoblasts." (PMID 26379475, 2015). "Chemokine C-X-C ligand 1 (CXCL1) was injected in the joints of syndecan-3−/−and wild-type mice and antigen-induced arthritis performed." (PMID 25015005, 2014). "The injection of NAc was also associated with an increase in the levels of pro-inflammatory cytokines and chemokines assayed, although only the increase in IL-1 and CXCL1 reached statistical significance, as compared to levels in animals subjected to mBSA arthritis that received saline." (PMID 36389831, 2022).
Arthritis (continued). "CXCL1 has been shown to be required for full arthritis development in C3H mice, and increased expression of this gene in B6 miR-146a−/− mice could be directly contributing to arthritis development through recruitment of neutrophils." (PMID 24967703, 2014). "Myeloid cells exhibit excessive proliferation and infiltration into joint tissue of B6 miR-146a−/− mice, have increased phagocytic activity and produce excess cytokines such as IL-1β, IL-6 and CXCL1, leading to inflammation of synovial tissue and arthritis development." (PMID 24967703, 2014). "This is in contrast to arthritis-susceptible B6 IL10−/− mice, where previously published data show that in addition to upregulation in IL-1β, IL-6, Cxcl1 and Cxcl2, IFNγ and Cxcl10 are upregulated 16-fold and 141-fold at 2 weeks, and 22-fold and 189-fold at 4 weeks, respectively." (PMID 24967703, 2014). "Another way that mast cells might drive arthritis was proposed to be through the release of tryptase/heparin complexes, which were shown to induce the expression of the neutrophil chemoattractants, CXCL1, CXCL5, and CXCL8, in cultured fibroblast-like synoviocytes." (PMID 27313578, 2016). "At the acute inflammatory phase of arthritis, an increase in pro-inflammatory cytokines occurred in aortas as attested by the increased mRNA expression of IL-6, TNF-α, and CXCL-1 (the IL-8 murine equivalent) in AIA." (PMID 35488311, 2022). "We measured CXCL1, CXCL5 IL-6, IL-8, IL-10, TNFα, and total IgG levels in the aliquots of set 1 and set 2 in eight arthritis patients." (PMID 34998422, 2022). "In contrast, in arthritis and some other conditions, IL-33 serves as a pro-inflammatory cytokine and exacerbates inflammation and pain via promoting the production of TNF-α, CXCL1, IL-1β and PGE2 through ST2 in plantar skin tissues 37-39." (PMID 33204337, 2020). "ICAM-1 and CXCL-1 expression increased in AIA rats at the preclinical phase and at the onset of arthritis while VCAM-1 increased only at the onset of arthritis." (PMID 35488311, 2022). "Dysregulation of Cxcl1 in these mice was particularly interesting because previous studies have shown that C3H mice lacking CXCL1 have reduced neutrophil infiltration and arthritis." (PMID 24967703, 2014). "Among all genes tested, the expression levels of Cxcl1, Mcp1, Il-1b, and Il-6 were significantly upregulated in the DRG after arthritis remission whereas no significant changes in Tnfα mRNA expression in the DRG were observed." (PMID 35833115, 2022). "Aortic vascular mRNA expressions of IL-6 and CXCL-1 were positively correlated while ICAM-1 and VCAM-1 negatively correlated with arthritis score and with radiographic score." (PMID 35488311, 2022). "Treating the 5-mo-old DNase II−/−STINGS365A/S365A mice with anti–IL-6R reduced the arthritis score and the expression of IL-6 and MMP-3 but did not reduce the expression of TNF-α, CXCL1, and CXCL2." (PMID 34901991, 2022). "The present study revealed that increased mRNA expression of adhesion molecules (ICAM-1) and CXCL-1 (IL-8) occurred as early as at the preclinical phase of AIA and reached its maximum at the onset of arthritis (ICAM-1, VCAM-1, IL-8) without any changes at the acute inflammatory phase." (PMID 35488311, 2022).
viral infection (34 papers, 2005 to 2025). "The choice of cytokines was based on the known role of these molecules in the context of neuropathology, either by mediating inflammation (IL-6, IL-1β, TNFα, CCL5, CXCL1) and/or by their association to viral infections (IFNs)." (PMID 28330482, 2017). "There was also an unexpected downregulation of genes associated with viral infection and several inflammatory pathways, including TNF, chemokine, and IL‐17 signaling, (e.g., CXCL1 and CXCL8)." (PMID 39836544, 2025). "Following the Delta P80 virus infection, the levels of CXCL1 in the lung washes became apparent around day 2 and 3 p.i.." (PMID 39652608, 2024). "The results showed that phillyrin treatment alleviated pneumonia induced by virus infection and significantly ameliorated the upregulation of multiple pro-inflammatory cytokines and chemokines (e.g., IL-1β, CXCL1, CCL3, CCL2, CCL5 and so on) in BALF." (PMID 37957672, 2023). "The local production of the proinflammatory mediator CXCL1 is concomitant to viral infection and in line with the presence of granulocytes in dermis, muscle and fascia." (PMID 36902230, 2023). "While investigating the involvement of the CXCL1-3/CXCR2 axis in dsRNA (Poly IC)-induced viral infection of the lung, it was discovered that the expression of CXCR2 and its ligands, CXCL1 and CXCL2/3, tallied with the recruitment of neutrophils to the lung." (PMID 36164329, 2022). "As assessed by ELISA using lung tissue homogenates, viral infection provoked a 2.4-fold increase in lung CXCL1 compared to the Air group." (PMID 34203121, 2021). "Viral infection-primed expression of type I IFNs is sufficient to interfere with production of specific chemokines, such as CXCL1 and CXCL2, resulting in impairment of the neutrophil response during secondary S. pneumoniae infection." (PMID 34061598, 2021). "Increased levels of CCL2 and CXCL1 have also been reported in neutrophil- and monocytes-infiltrated tissues in different viral infections." (PMID 33858301, 2021). "In a BCSFB model using human choroid plexus papilloma cells, a viral infection with Echovirus 30 showed an enhanced secretion of Cxcl1, Cxcl2, Cxcl3, and Ccl5." (PMID 32645014, 2020). "Oncolytic herpes simplex virus–resistant Ewing sarcoma tumors that express IL-1β, IL-6, and CXCL1 induce CD11b+ cell expression of VEGF after virus infection." (PMID 28536380, 2016). "We also found viral exacerbation to correlate with inhibition of neutrophil and NK cell recruitment early in the viral infection, as well as reduction in the levels of the chemokines KC (CXCL1) and MCP-1 (CCL2), which are chemoattractants for these cells." (PMID 21533103, 2011). "Within the context of viral infections, experimental data from mice infected with Theiler murine encephalomyelitis virus have demonstrated that CXCL1 released from epithelial cells, macrophages, and neutrophils recruits both neutrophils and monocytes to sites of infection." (PMID 30791481, 2019). "Similarly, upon viral infection, CXCL1 protein expression was reduced in caveolin-1 -/- mice as compared to wild type mice (p=.0001)." (PMID 24147000, 2013). "Viral infection induces a variety of proinflammatory cytokines and chemokines including IL-1b, IL-6, TNFa, CCL2, CCL3, CXCL1, CXCL2, CXCL9 and CXCL1034,35." (PMID 38750107, 2024). "It was associated with higher neutrophil recruitment by increased levels of CXCL1/2, CXCR2, and interleukin 1β (IL-1β) at a later stage of viral infection." (PMID 36005818, 2022). "Previous studies have shown that hepatocytes produce a number of chemokines, such as MCP-1, CXCL-1 and CXCL-10, which are upregulated after viral infection or liver injury and play an important role in the induction of hepatic inflammatory responses." (PMID 29867111, 2018).